CASP1 (caspase 1)
Diseases named in the same sentence as CASP1 in open-access papers (continued):
Sharing a sentence is not in itself a finding about the gene and the disease.
Anxiety (27 papers, 2017 to 2025). Intense feelings of nervousness, tension, or panic often arise in response to interpersonal stresses. "Caspase-1–deficient mice, compared to wild-type mice, showed decreased floating time in the forced swim test, decreased anxiety-like behavior as measured by the unaltered open/closed arms time ratio in the elevated plus-maze." (PMID 33362788, 2020). "In mice, the genetic deficiency of caspase-1, the effector molecule of the inflammasome, is associated with a decrease of innate and stress-induced depressive- and anxiety-like behaviors and affects chronic restraint stress response with a possible involvement of the intestinal microbiota." (PMID 33362788, 2020). "Inhibition of NLRP3 with a small molecule inhibitor MCC950 significantly reduced stress-induced anxiety in mice and IL1β as well as Caspase 1 activity." (PMID 34895246, 2021). "Ibrutinib-treated mice show marked reduction in stress-induced anxiety, IL1β levels and Caspase 1 activity in the hippocampus and amygdala." (PMID 34895246, 2021). "(Casp1, Ifngr, Nos2)−/− mice displayed decreased levels of depressive- and anxiety-like behaviour while exhibiting increased locomotor activity and moving velocity." (PMID 31015500, 2019). "The present study shows that stress accumulation causes an increase in extracellular ATP, the assembly of NLRP3 inflammasome, the cleavage of caspase-1, mature of IL-1β in the hippocampus as well as the depressive-like and anxiety-like behaviors in rodents." (PMID 28486969, 2017). "However, it also reduces ROS production and blocks the activation of the NLRP3-Caspase-1 signaling pathway, thus reducing anxiety and stress, so it is recommended to incorporate kidney beans into a routine diet." (PMID 38690099, 2024). "The expression levels of genes such as caspase-1 were significantly downregulated, suggesting that strain WLR01 might alleviate anxiety symptoms in SD mice by suppressing the activation of the NLRP3/caspase-1 pathway." (PMID 39339809, 2024). "Moreover, (Casp1, Ifngr, Nos2)−/− mice displayed decreased levels of anxiety-like behaviour in the elevated plus maze, as they spent more time in the open arms of the maze compared to wt mice." (PMID 31015500, 2019). "Activated caspase-1 cleaves Pro-IL-1β and Pro-IL-18 into their active forms, IL-1β and IL-18, thereby stimulating hippocampal inflammatory cells, exacerbating inflammation, promoting the formation of neurotoxic A1 astrocytes, and inducing depressive-like behaviors such as anxiety and despair." (PMID 39114351, 2024). "Here, we show that mice deficient in inflammasome regulators, including caspase-1 (Casp1), NLR family pyrin domain containing 3 (Nlrp3), IL-1 receptor (Il-1r), and gasdermin D (Gsdmd), exhibit behavior abnormalities characterized by hyperactivity and low anxiety levels." (PMID 33414187, 2021). "Collectively, our findings indicate that BPA triggers anxiety-like behaviors and pyroptotic death of nerve cells via the NF-κB/IL-1β/NLRP3/Caspase-1 pathway." (PMID 38941031, 2025). "Similarly, in a traumatic brain injury (TBI) model, genistein alleviated neurological deficits and anxiety-like behaviors by downregulating NLRP3 and caspase-1 expression, suggesting a central role in neuroinflammatory regulation." (PMID 41433336, 2025). "Maternal resource deprivation interacts with gestational exposure to diesel exhaust particles (DEP) by inducing long-term offspring anxiety-like behavior and sex-specific gene expression changes; e.g., only male offspring with prenatal DEP and maternal stress showed increased Tlr4 and Casp1." (PMID 34429070, 2021).
steatosis (27 papers, 2013 to 2025). Increased lipid within the cytoplasm of cells. "Using an IL-1 receptor antagonist, or mice deficient in CASP1 or ASC, the study demonstrated that CASP1-mediated IL1β signaling is necessary for the development of steatosis, inflammation, and injury in ALD." (PMID 33353156, 2020). "A study showed that IL-1 receptor (IL-1R) knockout mice and mice deficient in the inflammasome components casp-1 or Asc had decreased alcohol-induced liver injury, steatosis and inflammation." (PMID 32106390, 2020). "In another recent study from the same group, it was shown that mice deficient for caspase-1 and caspase-11 were protected from high fat-induced steatosis, inflammation and early fibrogenesis." (PMID 24312444, 2013). "Some studies have found that Caspase-1 is associated with steatosis, and treatment with the Caspase-1 inhibitor VX765 in mice with alcohol-induced liver injury results in reduced hepatic lipid deposition and lower serum TG levels, which in turn decreases liver injury." (PMID 40582769, 2025). "Indeed, caspase-1 deficient mice are protected from high-fat diet induced accumulation of circulating triglycerides, hepatic steatosis and inflammation." (PMID 38918843, 2024). "Animal experiments have shouwn upregulation of NLRP3, ASC, and Caspase-1 gene levels in the liver of NAFLD animals with steatosis." (PMID 38566171, 2024). "Inhibition of IL-1β or deletion of ASC and caspase-1 ameliorate inflammation, steatosis and liver injury in mice." (PMID 35173541, 2022). "The involvement of NLRP3 inflammasome in ALD has been demonstrated by a robust expression of NLRP3, caspase-1 and IL-1β in alcohol-fed mice, while liver inflammation and steatosis are dramatically attenuated in NLRP3−/− or caspase-1−/− mice." (PMID 30319645, 2018). "Although both groups of mice developed hepatic steatosis, caspase-1 KO mice displayed significantly less hepatic inflammation and steatosis." (PMID 27942420, 2016). "Magnoflorine was found to promote Parkin/PINK1-mediated mitochondrial autophagy, thereby inhibiting NLRP3/Caspase-1-mediated pyroptosis, ultimately decreasing tubular cell steatosis, lipid deposition, tubular dilation, and glomerular fibrosis in chronic kidney disease." (PMID 40520024, 2025). "In conclusion, our research results show that BSP-1 can improve liver injury and steatosis caused by MASLD in both in vitro and in vivo experiments, this effect may be attributed to the regulation of the pyrother-related NLRP3/caspase-1/GSDMD pathway." (PMID 40626309, 2025). "In addition, the decreased expression of ASC, caspase-1 p20, and GSDMD suppressed the hepatocyte pyroptosis pathway, which improved the inflammation, steatosis, and cell damage associated with pyroptosis, thereby alleviating NASH." (PMID 38547097, 2024). "Compared with the SBS group, the SBS+MFGM group showed lower liver pathology scores of steatosis and inflammation, less MPO positive cells and reduced expressions of NLRP3, apoptosis-associated speck-like protein containing a CARD (ASC), Caspase-1, interleukin (IL)-1β(P < 0.05) in the liver." (PMID 35308293, 2022). "In addition, we observed an apparent elevation in the mRNA levels of Caspase-1 in the ethanol-treated acute steatosis mouse liver compared with those in the liver of control mice." (PMID 33381029, 2020). "We found that caspase-1 knockout (KO) mice exhibited much less hepatic steatosis and inflammation." (PMID 27942420, 2016). "Increased adiposity in Casp1-/- mice may contribute to their protection from diet-induced steatosis." (PMID 23409132, 2013). "Another way in which caspase-1 may contribute to steatosis is via regulation of cytokine and chemokine expression in the liver." (PMID 23409132, 2013).
steatosis (continued). "The activation of NLRP3 inflammasome followed by caspase-1 activation allows the release of proinflammatory cytokines, such as IL-1β and IL-18, into the extracellular space that promote inflammatory cell death (pyroptosis), leading to an increase in liver inflammation, steatosis, and fibrosis." (PMID 35563780, 2022). "Compared with patients with steatosis alone (NAFL), patients with NASH have a significantly increased level of apoptosis, as well as pyroptosis with elevated expression of caspase-1 and necroptosis with increased expression of RIP3." (PMID 39244571, 2024). "Evidence supporting a crucial role of NLRP3 activation in ALD includes the marked protection of mice with global knockout of caspase-1, ASC, and IL-1β receptor which exhibit alleviated steatosis and inflammation." (PMID 35563780, 2022). "CASP1 KO, ASC KO, or NLRP3 KO mice were fed MCD for 24 days, and all displayed increased transaminases, worsening inflammation, and steatosis compared to WT controls." (PMID 33353156, 2020). "Methionine- and choline-deficient diet (MCDD) or prolonged high fat diet (HFD) induced murine NASH characterized by steatosis and immune cell infiltrates, display increased hepatic mRNA expression of IL-1β, NLRP3, caspase 1, and ASC alongside elevated caspase-1 activity." (PMID 35087852, 2021). "Caspase-1 plays a role in protecting non-monocytic cells, such as hepatocytes, from steatosis, whereas it contributes to the production of inflammatory cytokines in monocytic cells, like Kupffer cells." (PMID 23409132, 2013). "Taken together, the present data suggest that caspase-1 is expressed and functional in multiple cell types of the liver at different times of high fat diet-induced NASH, promoting steatosis, inflammatory cytokine production and the activation of HSC leading to early fibrogenesis." (PMID 23409132, 2013). "Therefore, BSP-1 plays a role in alleviating MASLD by preventing steatosis, inflammation, and pyroptosis, which may be relate to the inhibition of NLRP3/caspase-1/GSDMD signaling pathway." (PMID 40626309, 2025). "Indeed, steatosis progression to steatohepatitis and fibrosis originates from the uncontrolled increase of oxidative damage and inflammatory cascade and then is sustained by the activation of NLRP3 inflammasome which promotes Casp1-dependent IL-1β production." (PMID 33265944, 2020). "The analysis of the mRNA levels showed a significant increase in both the deleterious [Chop/Grp78] ratio (54-fold increase), and inflammasome components (caspase-4, caspase-1 and IL-1β) in NASH patients (n=9) compared with patients without NAFLD (n=6) and with steatosis (n=15)." (PMID 26355342, 2015).
injury (26 papers, 2016 to 2026). Damage inflicted on the body as the direct or indirect result of an external force, with or without disruption of structural continuity. "Furthermore, the activation of NLRP3 is closely associated with secretion of mature-IL-1β and cleave-caspase-1, which are closely related to the pathogenesis of liver injury." (PMID 33364966, 2020). "A previous study showed that caspase-1 activity was increased during the development of cisplatin-induced kidney injury and caspase-1-deficient mice were protected from cisplatin-induced nephrotoxicity, suggesting that caspase-1 is a key mediator of cisplatin-induced kidney injury." (PMID 30670928, 2018). "■NF-κB signaling suppression in mice with LPS-induced acute lung injury;■NLRP3 inflammasome and pro-caspase-1 complex assembly inhibition in mice with acute lung injury." (PMID 40298549, 2025). "This is achieved through the regulation of the NF-κB/NLRP3/caspase-1 signaling pathway, highlighting the potential of Salidroside as a preventative therapy for such environmental lung injuries." (PMID 41292520, 2025). "NLRP3 inflammasomes are involved in the inflammatory process of acute lung injury, and their activation can trigger caspase-1 maturation and ultimately induce caspase-1-dependent cell pyroptosis." (PMID 40520196, 2025). "Consistently, the inhibition of the NLRP3 inflammasome, which activates caspase-1 to promote the maturation and release of IL-18, has also been shown to reduce inflammatory cytokines after traumatic brain injury." (PMID 39858411, 2024). "Resveratrol alone has been shown to induce autophagy and evoke anti-inflammatory responses in retinal pigment epithelium cells, as well as inhibit NLRP3 inflammasome expression, caspase-1 activation, and IL-1β secretion in a mouse model of acute lung injury." (PMID 37375772, 2023). "We previously showed that the autophagy inhibitor chloroquine (CQ) increases inflammatory cleaved caspase-1 activity in myocytes, and that caspase-1/11 is protective in sterile liver injury." (PMID 32641037, 2020). "The hyper-inflammation was alleviated by AC-YVAD-CMK pretreatment, suggesting that preventing caspase-1 activation has an anti-inflammatory effect on acute gastric injury." (PMID 27053298, 2016). "Notably, caspase-1, IL-1β, and IL-18, the well-known markers of pyroptosis, which have been shown to be increased in other disease states such as lung injury, kidney inflammation, cardiomyopathy, and liver damage, were increased after Dox treatment." (PMID 33316945, 2020). "Furthermore, Isorhamnetin was speculated to have cytoprotective potential by suppressing by NLRP3 and caspase 1, in a model of acetaminophen-induced liver injury." (PMID 40257540, 2025). "This is consistent with findings from previous literature showing that the inhibition of XBP1 activity reduced NLRP3 inflammasome assembly and caspase-1 processing in a model of hepatic ischemia-reperfusion, thus reducing IRI-triggered liver injury." (PMID 36801911, 2023).
prostate carcinoma (26 papers, 2007 to 2025). A carcinoma that arises from epithelial cells of the prostate gland. "The inflammasome complex proteins ASC (apoptosis-associated speck-like protein containing a CARD) and pro-caspase-1, as well as its downstream targets IL-1β and IL-18 were confined to aggressive prostate cancer cells." (PMID 28663562, 2017). "Our results suggest that silencing IgG1 may be a novel approach to increasing caspase-3, and possibly caspase-1, to correct the loss of apoptosis in prostate cancer." (PMID 28536629, 2016). "Another study used non-cancerous prostate cell line PNT2 treated with extracellular vesicles (EVs) isolated from advanced prostate cancer PC3 cells (PC3-EVs) as a model to assess caspase-1–mediated IL-1β maturation after 24 hours of EV treatment." (PMID 40718836, 2025). "A central role of the biochemical caspase cascade, implied in immune response and prostate cancer cell apoptosis, was studied to caspase-1, -3, and -9 expressions in normal and malignant human prostate samples." (PMID 39273277, 2024). "As a classical inflammatory signalling pathway, the Caspase-1 pathway plays a crucial role in promoting pyroptosis in prostate cancer cells." (PMID 36702978, 2023). "Some studies suggested that pyroptosis is involved in abnormal changes in signalling pathways in prostate cancer; the main pyroptosis pathways related to prostate cancer are the Caspase-1 pathway, Caspase-4/5/11 pathway and Caspase-3 signalling pathway." (PMID 36702978, 2023). "They indicated that the NLRP12 inflammasome related to pyroptosis can upregulate Caspase-1 and downstream IL-1 β and IL-18 to promote the occurrence and progression of prostate cancer." (PMID 36702978, 2023). "Caspase-1 also can induce apoptosis in response to various stimuli; for example, caspase-1 enhanced the apoptosis of DU-145 prostate cancer cells upon irradiation (0 to 9 Gy)." (PMID 36430236, 2022). "In this paper we showed that, compared to LNCaP cells, advanced-stage prostate cancer PC3 cells display constitutively high levels of active caspase-1 and actively secrete IL-1β." (PMID 34070682, 2021). "It would be of interest in the future to determine if overexpression or silencing of CYP1B1 affects eicosanoid levels in prostate cancer tissue and how individual eicosanoids affect caspase-1 expression and activity in vitro and in vivo." (PMID 32581794, 2020). "A decreased level of caspase-1 protein expression was reported in primary prostate cancer compared with normal prostate tissues." (PMID 30042341, 2018). "The level of inflammasome adaptor proteins ASC and pro-caspase-1 was variable across the prostate cancer cell lines." (PMID 28663562, 2017). "Among these, CASP1 has been shown to be significantly down-regulated in prostate cancer and its genetic restoration reduces the tumorigenic potential by increasing apoptotic sensitivity." (PMID 28388569, 2017). "To further understand the role of inflammasomes in prostate cancer, we analyzed the protein expression of inflammasome sensors NLRP3 and NLRP12, and its associated proteins ASC and pro-caspase-1." (PMID 28663562, 2017). "Over-expression of caspase 1 enhances the sensitivity of androgen-independent prostate cancer cells to radiation-induced death." (PMID 26871479, 2016). "Caspase 1 was reported to have tumor suppressor properties and is frequently down-regulated in human cancers, prostate cancer in particular." (PMID 26871479, 2016). "Knockdown of GPR160 in prostate cancer cells increased the expression of caspase 1 and IL-6, induced cell cycle arrest and apoptosis, though the underlying molecular mechanism remains to be identified." (PMID 26871479, 2016). "In support, it has been demonstrated that caspase-1 is down-regulated in human prostate cancers, and reintroduction of caspase-1 leads to greater sensitivity to radiation-induced killing in vitro." (PMID 26689911, 2015).